CDC42BPA (CDC42 binding protein kinase alpha)
Description:
Serine/threonine-protein kinase which is an important downstream effector of CDC42 and plays a role in the regulation of cytoskeleton reorganization and cell migration. Regulates actin cytoskeletal reorganization via phosphorylation of PPP1R12C and MYL9/MLC2. In concert with MYO18A and LURAP1, is involved in modulating lamellar actomyosin retrograde flow that is crucial to cell protrusion and migration. Phosphorylates: PPP1R12A, LIMK1 and LIMK2. May play a role in TFRC-mediated iron uptake. In concert with FAM89B/LRAP25 mediates the targeting of LIMK1 to the lamellipodium resulting in its activation and subsequent phosphorylation of CFL1 which is important for lamellipodial F-actin regulation (By similarity). Triggers the formation of an extrusion apical actin ring required for epithelial extrusion of apoptotic cells.
Synonyms: KIAA0451; MRCKA; PK428; FLJ23347; MRCKalpha; MRCK
Tractability: Small molecule: a high-quality ligand is known; it belongs to a druggable protein family. Antibody: the Human Protein Atlas places it where antibodies can reach. PROTAC: ubiquitination databases record sites on it; its protein half-life has been measured; a small molecule that binds it is known.
Target class: Kinase; Protein Kinase; AGC protein kinase DMPK family; AGC protein kinase GEK subfamily; AGC protein kinase group; Enzyme
Gene: Protein-coding gene on chromosome 1 (226,989,865 to 227,318,492, reverse strand). Ensembl gene ENSG00000143776.
Subcellular location: Cytoplasm; Cell projection, lamellipodium
Subcellular location (Human Protein Atlas): Cytosol; Plasma membrane
Pathways (Reactome):
Signal Transduction: CDC42 GTPase cycle; RAC1 GTPase cycle; RHOJ GTPase cycle; RHOQ GTPase cycle
Gene Ontology:
Molecular function: ATP binding; identical protein binding; magnesium ion binding; protein binding; protein serine kinase activity; protein serine/threonine kinase activity; protein kinase activity
Biological process: actin cytoskeleton organization; actomyosin structure organization; cell migration; protein phosphorylation; cytoskeleton organization
Cellular component: actomyosin; extracellular exosome; cell leading edge; cell-cell junction; cytoplasm; cytoskeleton; cytosol; lamellipodium
Genetic constraint (gnomAD): Loss-of-function variants: 34 observed, 97.66 expected, observed/expected ratio (o/e) 0.35, 90% interval 0.26 to 0.46. The upper end of that interval is the gene's LOEUF score, 0.46, which puts it in group 2 of 6, group 1 being the genes least tolerant of losing a copy. Missense variants: 966 observed, 1,209.4 expected, observed/expected ratio (o/e) 0.8, 90% interval 0.76 to 0.84. Synonymous variants: 394 observed, 426.91 expected, observed/expected ratio (o/e) 0.92, 90% interval 0.85 to 1.
Homologues: Orthologues: macaque CDC42BPA (99% identical), chimpanzee CDC42BPA (98% identical), pig CDC42BPA (98% identical), rabbit CDC42BPA (98% identical), mouse Cdc42bpa (94% identical), rat Cdc42bpa (94% identical), guinea pig CDC42BPA (88% identical), tropical clawed frog cdc42bpa (80% identical), zebrafish cdc42bpab (72% identical), zebrafish cdc42bpaa (68% identical), Drosophila melanogaster gek (43% identical), Caenorhabditis elegans mrck-1 (37% identical). Paralogues in human: CDC42BPB (61% identical), CDC42BPG (42% identical), CIT (24% identical), ROCK2 (21% identical), ROCK1 (20% identical).
Diseases named in the same sentence as CDC42BPA in open-access papers:
CDC42BPA is named in the same sentence as 46 diseases in open-access papers, as found by Europe PMC text mining. Sharing a sentence is not in itself a finding about the gene and the disease. The quoted sentences say what the papers report.
breast carcinoma (13 papers, 2011 to 2024). "Interestingly, microarray analysis identified the increased expression of Cdc42BPA mRNA (identified in the study as PK428) as being significantly associated with an increased risk of breast cancer metastasis." (PMID 36831201, 2023). "Kaplan–Meier OS analysis of breast cancer patients revealed that low expression of FBXW7, SRGAP2, MTMR3 as well as CDC42, the partner of CDC42BPA, is associated with poor prognosis." (PMID 37463901, 2023). "Opposing correlations between CDC42 and CDC42BPA expression and OS are also seen in basal-like breast cancer." (PMID 37463901, 2023). "In contrast, low expression of CDC42BPA marks breast cancer patients with better prognosis." (PMID 37463901, 2023). "However, the analysis revealed 3 somatic mutated genes: CDC42BPA, EXT1, and PRC1 significantly associated with both types of breast cancer." (PMID 32724790, 2020). "However, Oncoprint analysis of CDC42BPA reveals deep deletions of the gene are almost exclusively found in metastatic but not primary breast cancer, suggesting that loss of this gene may promote metastasis." (PMID 37463901, 2023). "Sixteen understudied kinases showed strong variance between TNBC and HER2/luminal breast cancer, with higher-ranked understudied kinases being DAPK3, ADCK1, MRCKA (CDC42BPA), STK17A, DMPK and VRK2." (PMID 29643987, 2018). "For breast cancer, of the six predicted candidates (PRKCQ, ARAF, MAPK14, BRMS1, CDC42BPA, SP3), three (PRKCQ, ARAF, MAPK14) are members of at least one KEGG cancer relevant pathway." (PMID 25961669, 2015). "To analyze the requirement of MRCKα for breast cancer, we first generated mice lacking a functional MRCKα gene (Cdc42bpa) using CRISPR genome editing." (PMID 33921698, 2021).
colorectal cancer (2 papers, 2020 to 2022). A primary or metastatic malignant neoplasm that affects the colon or rectum. "A further functional study has indicated that miR−29a−3p inhibits cell migration and invasion of a colorectal cancer cell line by suppressing CDC42BPA mRNA expression." (PMID 33014873, 2020).
pancreatic cancer (2 papers, 2016 to 2017). "CDC42BPA encodes a member of the Serine/Threonine protein kinase family and is upregulated in pancreatic cancer, a smoking related cancer, compared to normal tissue." (PMID 29207374, 2017).
acute lower respiratory infection (1 paper, 2022). "Both ASB4 and CDC42BPA showed an association with COPD with acute lower respiratory infection." (PMID 36194576, 2022).
allergic asthma (1 paper, 2015). A asthma with a basis in a pathological type I hypersensitivity reaction. "Furthermore, the upregulated genes (PDPK1, EZR, MYO6, CDC42BPA, OPHN1, ARF6 and WASL) identified in the present study that were enriched in the actin filament-based process require further study in order to determine whether they may be used as potential biomarkers of allergic asthma." (PMID 25633562, 2015).
lung carcinoma (1 paper, 2022). "In PhenoScanner, 6 out of 12 hub genes (IRAK2, MECOM, ASB4, CDC42BPA, DPF3 and TMEM67) have revealed an association with lung related traits and lung cancer." (PMID 36194576, 2022). "Other COPD- hub genes (CDC42BPA, ASB4, DPF3 and TMEM67) are were also associated with lung function related traits and lung cancer." (PMID 36194576, 2022). "Additional COPD hub genes like SREK1, TMEM67, CDC42BPA, DPF3, and ASB4 were identified as prognostic markers in lung cancer, which is reported in 1% of COPD patients." (PMID 36194576, 2022). "Medium staining detection of CDC42BPA and IRAK2 were found in both normal and cancer lung tissue in addition to SREK1 and C1QTNF2 which was observed in medium in normal tissue but higher in lung cancer tissue." (PMID 36194576, 2022). "Interestingly, we have also identified that the expression status of other COPD hub genes like SREK1, TMEM67, CDC42BPA, DPF3, and ASB4 improves the survival duration of lung cancer patients, hence they may act as potential molecular drug targets and/or biomarkers for both COPD and/or lung cancer." (PMID 36194576, 2022).
posterior fossa ependymoma (1 paper, 2022). A high grade ependymoma that is located within the posterior fossa. "Interestingly, 6/7 of the constrained genes in which pLoF variants were found in patients with posterior fossa ependymoma show particularly high expression levels in cerebellar tissue (UHRF2, FOXO3, CDC42BPA, ZMYM2, CHD6 and DNAJC2)." (PMID 36008825, 2022).
pulmonary stenosis (1 paper, 2020). "We also report novel plausible gene–disease associations for tetralogy of Fallot/pulmonary stenosis (CDC42BPA, FGD5), hypoplastic left or right heart (SMARCC1, TLN2, TRPM4, VASP), congenitally corrected transposition of the great arteries (UBXN10), and early-onset cardiomyopathy (TPCN1)." (PMID 32037394, 2020).
cancer (24 papers, 2011 to 2024). A tumor composed of atypical neoplastic, often pleomorphic cells that invade other tissues. "Eight understudied kinases were found to have hotspot mutations in at least one cancer (CDC42BPA, DYRK1B, DYRK4, LMTK3, MAPK15, NEK7, TSSK1B, and TTBK1), with DYRK4, LMTK3, MAPK15, and NEK7 all having significant hotspot mutations in STAD." (PMID 33205077, 2020). "Data from The Cancer Genome Atlas (TCGA) pan-cancer atlas compiled from 32 studies indicated that 9% of the 10,953 patients had genomic alterations to one or more of the Cdc42BPA, Cdc42BPB, and Cdc42BPG genes, with gene amplifications and missense mutations being the most common." (PMID 36831201, 2023).
tumor (13 papers, 2011 to 2025). "Levels of these five transcripts were also decreased in NSCLC cells (A549 and H1299) upon overexpression of miR‐515‐5p (although not significantly for CDC42BPA in A549 cells), underlying a common molecular function for this miRNA across tumour types." (PMID 26882547, 2016).
CDC42BPA also shares sentences with these, for which no sentence is quoted: myotonic dystrophy (5 papers); skin cancer (4); squamous cell carcinoma (4); melanoma (3); glioma (2); infection (2); metastatic cancer (2); ovarian carcinoma (2); acute coronary syndrome (1); acute myeloid leukemia (1); acute respiratory distress syndrome (1); adenoid cystic breast carcinoma (1); asthma (1); autoimmune disease (1); Becker muscular dystrophy (1); breast tumours (1); cholestasis (1); cutaneous squamous cell carcinoma (1); depression (1); dyslexia (1); glioblastoma (1); hyperlipidemia (1); Insulin resistance (1); invasive breast carcinoma (1); invasive ductal breast carcinoma (1); lung disease (1); lung squamous cell carcinoma (1); mantle cell lymphoma (1); megalencephalic leukoencephalopathy (1); Obesity (1).
A further 6 diseases each share a sentence with CDC42BPA in 1 paper.